ARHGAP29 (Rho GTPase activating protein 29)
Description:
GTPase activator for the Rho-type GTPases by converting them to an inactive GDP-bound state. Has strong activity toward RHOA, and weaker activity toward RAC1 and CDC42. May act as a specific effector of RAP2A to regulate Rho. In concert with RASIP1, suppresses RhoA signaling and dampens ROCK and MYH9 activities in endothelial cells and plays an essential role in blood vessel tubulogenesis.
Synonyms: PARG1
Tractability: Antibody: the Human Protein Atlas places it where antibodies can reach. PROTAC: ubiquitination databases record sites on it.
Gene: Protein-coding gene on chromosome 1 (94,148,988 to 94,275,068, reverse strand). Ensembl gene ENSG00000137962.
Subcellular location (Human Protein Atlas): Centrosome; Nucleoplasm; Cytosol; Plasma membrane
Pathways (Reactome):
Signal Transduction: CDC42 GTPase cycle; RAC1 GTPase cycle; RHOA GTPase cycle
Gene Ontology:
Molecular function: PDZ domain binding; GTPase activator activity
Biological process: negative regulation of small GTPase mediated signal transduction; regulation of small GTPase mediated signal transduction; Rho protein signal transduction; signal transduction
Cellular component: cytoplasm; protein-containing complex; cytosol
Genetic constraint (gnomAD): Loss-of-function variants: 38 observed, 111.1 expected, observed/expected ratio (o/e) 0.34, 90% interval 0.26 to 0.45. The upper end of that interval is the gene's LOEUF score, 0.45, which puts it in group 1 of 6, group 1 being the genes least tolerant of losing a copy. Missense variants: 1,271 observed, 1,503.2 expected, observed/expected ratio (o/e) 0.85, 90% interval 0.81 to 0.89. Synonymous variants: 497 observed, 514.09 expected, observed/expected ratio (o/e) 0.97, 90% interval 0.9 to 1.04.
Homologues: Orthologues: chimpanzee ARHGAP29 (99% identical), macaque ARHGAP29 (97% identical), dog ARHGAP29 (87% identical), rabbit ARHGAP29 (87% identical), pig ARHGAP29 (84% identical), guinea pig ARHGAP29 (84% identical), mouse Arhgap29 (83% identical), tropical clawed frog arhgap29 (47% identical), zebrafish arhgap29b (41% identical), zebrafish arhgap29a (41% identical), Caenorhabditis elegans spv-1 (19% identical). Paralogues in human: ARHGAP45 (29% identical), GMIP (25% identical).
Diseases named in the same sentence as ARHGAP29 in open-access papers:
ARHGAP29 is named in the same sentence as 40 diseases in open-access papers, as found by Europe PMC text mining. Sharing a sentence is not in itself a finding about the gene and the disease. The quoted sentences say what the papers report.
gastric cancer (12 papers, 2017 to 2025). A primary or metastatic malignant neoplasm involving the stomach. "Although the results should be taken with care, one study showed the association of hepatitis with gastric cancer, and the link between the two might involve the Rho GTPase activator ARHGAP29, which has been previously associated with gastric cancer, and associated with hepatitis in this study." (PMID 37108169, 2023). "In CTCs, YAP transcriptionally upregulates Rho GTPase activation protein 29 (ARHGAP29) and hence promotes metastasis of gastric cancer." (PMID 34145217, 2021). "In gastric cancer, YAP was found to regulate F-actin dynamics through the transcription of genes encoding Rho GTPase-activating protein 29 (ARHGAP29)." (PMID 34205830, 2021). "As already described for renal and gastric cancer, ARHGAP29 influences the invasion and metastasis of malignant tumor cells." (PMID 33291460, 2020). "Recently, it was reported that YAP-induced ARHGAP29 promotes metastasis in a human gastric cancer cell line." (PMID 29673177, 2018). "For example, YAP drives the expression of ARHGAP29, which is required for gastric cancer metastasis, and YAP-mediated repression of Growth Differentiation Factor-15 promotes breast cancer metastasis." (PMID 29642615, 2018). "In gastric cancer, YAP promotes ARHGAP29 expression, which, in turn, inhibits the RhoA-LIMK-cofilin pathway and destabilizes F-actin, thereby promoting gastric cancer cell migration." (PMID 39744435, 2025). "Additionally, upregulation of ARHGAP29 might be related to metastasis in gastric cancer." (PMID 34222474, 2021). "Second, the Sudol group showed that an additional RhoGAP gene, ARHGAP29 (Rho GTPase Activating Protein 29), is a YAP transcriptional target in a human gastric cancer cell line." (PMID 33233821, 2020). "For example, a recent study found Rho GTPase activating protein 29 (ARHGAP29), a pro-metastatic YAP target gene in gastric cancer, suppresses a RhoA-LIM Domain Kinase (LIMK)-cofilin pathway to drive cell migration." (PMID 29642615, 2018).
breast carcinoma (5 papers, 2020 to 2025). "We were able to show that reduced ARHGAP29 expression in breast cancer cells is associated with reduced AKT1 levels." (PMID 33291460, 2020). "In summary, we showed, for the first time, that ARHGAP29 influences the invasive abilities of breast cancer cells." (PMID 33291460, 2020). "Aggressive and mesenchymal-transformed breast cancer cells show high expression levels of Rho GTPase activating protein 29 (ARHGAP29), a negative regulator of RhoA." (PMID 33291460, 2020). "Inspired by these considerations, AKT1 was investigated as a further target in addition to ARHGAP29 for expression analyses to compare breast cancer cells with reduced and normal ARHGAP29 expression and to investigate a possible signal cascade around ARHGAP29." (PMID 33291460, 2020). "ARHGAP29 is expressed to an increased extent in invasive and mesenchymal-transformed breast cancer cells." (PMID 33291460, 2020). "Proliferation of the breast cancer cell line T-47D-EMT was slightly increased by reduced expression of ARHGAP29, whereas that of HCC1806 and MCF-7-EMT significantly increased." (PMID 33291460, 2020). "At the same time, MCF-7 breast cancer cells show reduced cell–cell contact and increased migration properties after RhoA reduction, which is comparable to the suppressive effect of ARHGAP29." (PMID 33291460, 2020). "ARHGAP29 was the only one of 32 GTPase-activating enzymes whose expression significantly increased after the induction of mesenchymal transformation in breast cancer cells." (PMID 33291460, 2020). "After induction of EMT, ARHGAP29 was the only GAP upregulated in both mesenchymal-transformed breast cancer cell lines." (PMID 33291460, 2020). "We showed that downregulation of ARHGAP29 expression in the breast cancer cell lines examined (HCC1806, MCF-7-EMT, T-47D-EMT) was associated with significantly reduced invasiveness." (PMID 33291460, 2020). "T-47D-EMT breast carcinoma cells with reduced ARHGAP29 expression showed significantly reduced invasiveness compared with the control group (58.37 cells ± 9.317 cells SEM in % vs. control 100 cells ± 13.82 cells SEM in %; p = 0.0175; n = 18)." (PMID 33291460, 2020). "We investigated the effects of ARHGAP29 downregulation on the invasion and proliferation of breast cancer cells." (PMID 33291460, 2020). "Invasion assays were performed with breast cancer cells transiently transfected with ARHGAP29 siRNA and cells treated with control siRNA." (PMID 33291460, 2020). "Furthermore, ARHGAP29 plays an inhibitory role in the proliferation of breast cancer cells, whose proliferation can be significantly increased by ARHGAP29 knock-down." (PMID 33291460, 2020). "Therefore, we investigated the influence of ARHGAP29 on the invasiveness of aggressive and mesenchymal-transformed breast cancer cells." (PMID 33291460, 2020). "In addition, ARHGAP29 was the only one of 32 GTPase-activating enzymes with increased expression after epithelial–mesenchymal transformation of breast cancer cells." (PMID 33291460, 2020). "Our results show that ARHGAP29 could be an important factor in the invasion of aggressive and mesenchymal-transformed breast cancer cells." (PMID 33291460, 2020). "In this study, we analyzed whether changed ARHGAP29 expression influences the invasiveness of mesenchymal-transformed and aggressive breast cancer cells." (PMID 33291460, 2020). "Little is known about the role of ARHGAP29 in breast cancer." (PMID 33291460, 2020). "The 10-year overall survival of luminal A breast cancer patients with high expression of ARHGAP29 was significantly reduced as compared with luminal A breast cancer patients with low expression of ARHGAP29 (Threshold = 8 FPKM; ARHGAP29lown = 271; ARHGAP29highn = 209; p = 0.0141)." (PMID 33291460, 2020). "Since changes in proliferation could influence the results of invasion analyses, the breast cancer cells were analyzed with regard to a possible influence of a reduction of ARHGAP29 on their proliferation." (PMID 33291460, 2020).
breast carcinoma (continued). "The role of ARHGAP29 varies across different tumor types; for example, upregulated ARHGAP29 expression promotes proliferation and invasion of prostate cancer cells 18, and invasive, mesenchymally-transformed breast cancer cells exhibit elevated ARHGAP29 expression." (PMID 39744435, 2025). "Therefore, we analyzed the influence of ARHGAP29 on the invasiveness of breast cancer cell lines." (PMID 33291460, 2020). "Therefore, we investigated whether reduced ARHGAP29 expression influences bone-directed invasion of invasive breast cancer cells." (PMID 33291460, 2020). "However, it is unknown whether ARHGAP29 influences the ability of breast cancer cells to invade and proliferate and which signal cascade is involved." (PMID 33291460, 2020). "A recent study showed that Rho GTPase activating protein 29 (ARHGAP29) interacted with Akt1 and knockdown of ARHGAP29 decreased invasion of breast cancer cells." (PMID 34298660, 2021). "ARHGAP29 and AKT-1 expression was examined in a control group and in breast cancer cells transiently transfected with ARHGAP29-specific siRNA." (PMID 33291460, 2020). "After knock-down of ARHGAP29 using siRNA, invasion of HCC1806, MCF-7-EMT, and T-47D-EMT breast cancer cells was significantly reduced." (PMID 33291460, 2020). "Although numerous publications have discussed the signal cascade and the role of PI3K and the various AKT isoforms in breast cancer, crosstalk between ARHGAP29 and AKT1 signaling has not yet been reported." (PMID 33291460, 2020). "In addition, ARHGAP29 expression is increased in invasive breast cancer cells, and its transcriptional co-activator YAP promotes the invasion of breast cancer cells." (PMID 33291460, 2020).
cleft lip (4 papers, 2021 to 2025). Congenital defect in the upper lip where the maxillary prominence fails to merge with the merged medial nasal prominences. "Mutations in the Arhgap29 gene are significantly associated with non-syndromic cleft lip and palate (NSCL/P)." (PMID 40429791, 2025). "Our research group previously identified Arhgap29 as a target gene through genome-wide association studies (GWAS) and whole-exome sequencing of families affected by cleft lip and palate." (PMID 40429791, 2025). "Our findings underscore the critical role of Arhgap29 in the development of the mandible and digits, suggesting its potential as a pathogenic gene associated with syndromic cleft lip and palate (SCL/P)." (PMID 40429791, 2025). "Our study demonstrated that the deletion of Arhgap29 leads to syndromic cleft lip and palate (SCL/P) characteristics in mice, where, in addition to cleft palate, the mice exhibit craniofacial and systemic skeletal abnormalities." (PMID 40429791, 2025). "According to them, ARHGAP29 is a more plausible candidate for cleft lip and palate than ABCA4." (PMID 34769998, 2021). "Defects in ARHGAP29 may cause non-syndromic cleft lip with or without cleft palate." (PMID 35783123, 2022). "A maternally inherited splicing variant c.1920+1G>A was detected in the ARHGAP29 gene, which is not a known OMIM disease gene, but recorded in the Orphanet database for nonsyndromic cleft lip and palate (ORPHA:199306)." (PMID 36307859, 2022).
cleft palate (4 papers, 2020 to 2025). Cleft palate is a fissure type embryopathy that affects the soft and hard palate to varying degrees. "It remains unclear whether these changes are secondary to the cleft palate or whether they reflect a direct role of Arhgap29 in bone development." (PMID 40429791, 2025). "Moreover, de novo harmful rare variant NM_004815.3, NP_004806.3; c.1652G>C, p.R551T in ARHGAP29 resulted in a decreased expression level of ARHGAP29, which in turn affected NSCL/P-related biological processes; however, no overt cleft palate (CP) phenotype was observed." (PMID 36061182, 2022).
prostate carcinoma (4 papers, 2016 to 2025). A carcinoma that arises from epithelial cells of the prostate gland. "We and others have observed significant vimentin expression within PBMC cell populations; consequently, we used TaqMan assays targeting EpCAM and ARHGAP29 transcripts for specific identification of prostate cancer cells." (PMID 27189161, 2016). "ARHGAP29 is a GTPase that stimulates prostate cancer development and metastasis." (PMID 36568182, 2022).
orofacial clefting (3 papers, 2017 to 2025). "In summary, the finding of these variants and the predicted loss of important functional domains such as the RhoGap domain in ARHGAP29 increases the growing evidence implicating abnormal Rho GTPase signaling in the pathogenesis of orofacial clefts." (PMID 39506048, 2025). "For example, SNPs, such as the ones we identified, in the ABCA4 gene have previously been shown to be in enhancer regions which control ARHGAP29 expression and evidence suggests that it is ARHGAP29 not ABCA4 that plays a role in orofacial clefting." (PMID 41075272, 2025).
colorectal cancer (2 papers, 2025). A primary or metastatic malignant neoplasm that affects the colon or rectum. "However, further investigation is needed to elucidate the specific molecular mechanism and role of cytoskeletal remodeling by ARHGAP29 in colon cancer metastasis to identify new therapeutic targets for colorectal cancer." (PMID 39744435, 2025). "For instance, in colorectal cancer, TBX21 inhibits the proliferation of tumor cells and promotes their apoptosis by regulating the ARHGAP29/RSK/GSK3β signaling pathway." (PMID 41573646, 2025).
mantle cell lymphoma (2 papers, 2010 to 2017). Mantle cell lymphoma is a rare form of malignant non-Hodgkin lymphoma affecting B lymphocytes in the lymph nodes in a region called the ``mantle zone''. "A strong down-regulation of ARHGAP29, by several mechanisms such as deletion and promoter methylation, was found in all mantle cell lymphoma (MCL) samples, which may lead to carcinogenesis through the dysregulation of Rho/Rac/Cdc42-like GTPases." (PMID 20504321, 2010). "Furthermore, we found up-regulation of ARHGAP29 that belongs to the Rho GTPase activating proteins (ARHGAP) which are involved in brain development, modulation of circadian genes and show potential tumour suppressor activity in mantle cell lymphoma." (PMID 29281661, 2017).
arterial hypertension (1 paper, 2023). "Here, we analyzed localization patterns of ARHGAP29 in mildly damaged glomeruli in the context of chronic kidney disease with arterial hypertension and observed increased levels of ARHGAP29 in minimally damaged glomeruli." (PMID 37443829, 2023).
bipolar disorder (1 paper, 2022). A disorder of the brain that causes unusual shifts in mood, energy, activity levels and the ability to carry out day-to-day tasks. "These are associated with a variety of neurological diseases, such as cognitive defects (ARHGAP15), migraine without aura (ARHGAP28), AD (ARHGAP2), schizophrenia (ARHGAP18), and bipolar disorder (BD; ARHGAP29; Niftullayev and Lamarche-Vane, 2019)." (PMID 35783123, 2022).
cerebral cavernous malformation (1 paper, 2016). A disorder characterized by malformations in the structure of the capillaries in the brain. "Src activity has been reported to inhibit the Rho/Rock pathway, a pathway also inhibited by Pak2/Pak4, Rasip1/Arhgap29, and the cerebral cavernous malformation (CCM) proteins, CCM1 and CCM2." (PMID 26812085, 2016).
colon cancer (1 paper, 2025). "TBX21 inhibits the proliferation of colon cancer cells through an ARHGAP29/RSK/GSK3β-dependent mechanism." (PMID 39744435, 2025). "Recent studies have shown that ARHGAP29 is a direct target gene of TBX21, is positively regulated by TBX21, and plays an important role in inhibiting the proliferation and promoting apoptosis of colon cancer cells." (PMID 39744435, 2025).
diabetic nephropathy (1 paper, 2023). "In contrast, destructive glomerular diseases such as diabetic nephropathy (DN), focal segmental glomerulosclerosis (FSGS), and collapsing FSGS (cFSGS) showed reduced levels of ARHGAP29 expression." (PMID 37443829, 2023).
glioma (1 paper, 2020). A benign or malignant brain and spinal cord tumor that arises from glial cells (astrocytes, oligodendrocytes, ependymal cells). "It has been shown that ARHGAP29 expression is not only increased in migrating glioma cells and circulating tumor cells but is also associated with an increased tendency to metastasize." (PMID 33291460, 2020).
glomerular disease (1 paper, 2023). "In these data sets, ARHGAP29 mRNA expression appeared enriched in glomerular diseases usually presenting with milder damage patterns such as hypertensive nephropathy (HTN) and minimal change disease (MCD)." (PMID 37443829, 2023). "Future studies will have to investigate the role of ARHGAP29 in in vivo models of glomerular disease and its potential for targeted therapeutic approaches." (PMID 37443829, 2023). "Analysis in human kidney tissue showed increased ARHGAP29 expression in early glomerular disease stages." (PMID 37443829, 2023). "The extensive transcriptome and functional analysis further prompted us to investigate the potential role of ARHGAP29 in glomerular disease." (PMID 37443829, 2023). "Detection of increased levels of ARHGAP29 in early disease stages of human glomerular disease implies a novel negative feedback loop for mechanotransductive RhoA—YAP/TAZ signaling in podocyte physiology and disease." (PMID 37443829, 2023).
Hearing impairment (1 paper, 2023). A decreased magnitude of the sensory perception of sound. "and (EYA1_i003): p.(Arg106Ter) being found in isolated CLP cases on prenatal ultrasound, ARHGAP29 was more commonly associated with NSCL/CP, while EYA1 could cause hearing impairment or kidney abnormalities (OMIM #602588)." (PMID 37745857, 2023).
hepatocellular carcinoma (1 paper, 2025). A malignant tumor that arises from hepatocytes. "circTMEM181 inhibits hepatocellular carcinoma migration and invasion by sponging miR-519a-5p and upregulating ARHGAP29 expression." (PMID 39744435, 2025).
invasive breast carcinoma (1 paper, 2020). A carcinoma that infiltrates the breast parenchyma. "ARHGAP29 expression was increased in various invasive breast cancer cell lines." (PMID 33291460, 2020).
melanoma (1 paper, 2025). A malignant, usually aggressive tumor composed of atypical, neoplastic melanocytes. "Studies in non-melanoma cancer entities described that ARHGAP29 modulates the actin cytoskeleton, promoting tumor cell invasion." (PMID 40906537, 2025). "To summarize, this study gives insights into the functional role of ARHGAP29 and its downstream signaling in melanoma." (PMID 40906537, 2025). "Our transcriptomic analyses revealed a strong expression of ARHGAP29 in melanoma cell lines compared to melanocytes." (PMID 40906537, 2025). "Our findings provided evidence supporting the hypothesis that ARHGAP29 is an important player in melanoma progression, a promising and novel target in melanoma treatment." (PMID 40906537, 2025). "Therefore, we hypothesized that ARHGAP29 affects the migratory potential of melanoma cells and drives melanoma progression." (PMID 40906537, 2025).